KCNQ3 (potassium voltage-gated channel subfamily Q member 3)
Diseases named in the same sentence as KCNQ3 in open-access papers (continued):
Sharing a sentence is not in itself a finding about the gene and the disease.
cancer (3 papers, 2015 to 2023). A tumor composed of atypical neoplastic, often pleomorphic cells that invade other tissues. "Opposingly, KCNQ3 displays hallmarks of an oncogene, it is often amplified in cancers, mutations are mostly GoF, and cell proliferation/Wnt signalling increases when it is overexpressed in some contexts." (PMID 37748809, 2023). "In metastatic adenocarcinoma, there are an almost complete loss of KCNQ1 and a concurrent up-regulation of KCNQ3, confirming that KCNQ protein levels correlate with disease severity in a model of GOA cancer." (PMID 37748809, 2023). "Based on the apparent links between KCNQ genomic status and cancer from patient data, we next sought to establish how changes in KCNQ1 and KCNQ3 expression impact cancer cell phenotype." (PMID 37748809, 2023). "We also discover that activity of KCNQ3 sensitises cancer cells to existing potassium channel inhibitors and that inhibition of KCNQ activity reduces proliferation of GOA cancer cells." (PMID 37748809, 2023). "Both genes are in chromosomal regions commonly amplified in GI cancers (KCNQ2: chromosome 20q13.3; KCNQ3: chromosome 8q24.22) and known to be involved in cancer progression." (PMID 37748809, 2023). "Overall, 112 (12%) patients have a mutation/copy-number change in KCNQ3, and although the 8q24 locus is a known susceptibility indicator in many cancers, KCNQ3 has not previously been extensively explored in cancer." (PMID 37748809, 2023). "Furthermore, we have previously identified that KCNQ1 and KCNQ3 RNA expression correlates with a cancer gene expression profile." (PMID 37748809, 2023). "Only the three remaining genes, KCNQ3, LRRC38 and RP1, were rarely reported in any cancer research, and thus show potential value for research in LUSC." (PMID 35962453, 2022).
psychiatric disorder (2 papers, 2013 to 2025). A disorder characterized by behavioral and/or psychological abnormalities, often accompanied by physical symptoms. "Notably, SLIT2 and KCNQ3, previously linked to psychiatric disorders but without specific cell-type associations, exhibit cell-type–specific dysregulation." (PMID 40053590, 2025).
KCNQ3 also shares sentences with these, for which no sentence is quoted: benign familial infantile epilepsy (3 papers); Cognitive impairment (3); developmental disability (3); infection (3); long QT syndrome (3); Seizure (3); breast carcinoma (2); cortical visual impairment (2); developmental and epileptic encephalopathy (2); epilepsy syndrome (2); neurological disorders (2); Pain (2); Angelman syndrome (1); anxiety disorder (1); atrial fibrillation (1); attention deficit-hyperactivity disorder (1); brain disease (1); Brugada syndrome (1); channelopathies (1); colon adenocarcinoma (1); Dent disease (1); ependymoma (1); episodic ataxia (1); episodic ataxia type 1 (1); erythromelalgia (1); gastric adenocarcinoma (1); Hypertension (1); infantile spasms (1); ischemic stroke (1); Lewis lung carcinoma (1).
A further 10 diseases each share a sentence with KCNQ3 in 1 paper.